ACSL4 (acyl-CoA synthetase long chain family member 4)
Diseases named in the same sentence as ACSL4 in open-access papers (continued):
Sharing a sentence is not in itself a finding about the gene and the disease.
ovarian carcinoma (18 papers, 2021 to 2026). A malignant neoplasm originating from the surface ovarian epithelium. "In ovarian cancer, ACSL4 also facilitates M1 macrophage polarization, leading to inhibiting tumor progression." (PMID 41288931, 2025). "ACSL4 can attenuate the progression of prostate and ovarian cancers by promoting ferroptosis in cancer cells." (PMID 41288931, 2025). "miR-424-5p exerts a negative regulatory effect on ferroptosis in ovarian cancer cells through the targeting of ACSL4." (PMID 41049453, 2025). "Western blot assay revealed that POL increased the expression of ACSL4 in ovarian cancer cells as well as in tumors in mice in vivo." (PMID 38503553, 2024). "More importantly, the POL-mediated increase in lipid ROS, Fe2+, MDA, and decrease in GSH were significantly reversed after knocking down ACSL4 in ovarian cancer cells." (PMID 38503553, 2024). "Taken together, we conclude that POL inhibits ovarian cancer development by inducing ferroptosis in ovarian cancer cells through up-regulation of ACSL4." (PMID 38503553, 2024). "miR-424-5p inhibits ferroptosis and the cell death of ovarian cancer cells by targeting ACSL4, which is reversed by ACSL4 overexpression or miR-424-5p underexpression." (PMID 38892270, 2024). "Knockdown of miR-424-5p increases ferroptosis sensitivity of ovarian cancer cells by upregulating ACSL4 expression." (PMID 37626043, 2023). "Downregulation of miR-424-5p increased ACSL4 expression, a positive mediator of ferroptosis, which sensitized ovarian cancer cells to erastin and RSL3-induced ferroptosis." (PMID 36438923, 2022). "In ovarian cancer, miR-424-5p negatively regulates ferroptosis by directly targeting ACSL4 in ovarian cancer cells." (PMID 36187333, 2022). "Similarly, the upregulation of miR-424-5p reduced the sensitivity of HO8910 and SKOV3 ovarian cancer cells to RSL3-induced ferroptosis by inhibiting ACSL4." (PMID 37626043, 2023). "The high expression of ACSL4 indicates that the prognosis of patients with ovarian cancer is poor." (PMID 36147484, 2022). "Interestingly, they found that ACSL4 is remarkably overexpressed in ovarian cancer tissues and is positively correlated with the aggressive phenotypes of ovarian cancer." (PMID 36438923, 2022). "Thus, POL can effectively inhibit ovarian cancer development, which may be achieved by increasing ACSL4-mediated ferroptosis." (PMID 38503553, 2024). "But the upregulation of ACSL4 increased the effect of erastin and RSL3 induced ferroptosis in ovarian cancer cells." (PMID 36408273, 2022). "miR-424-5p inhibitor can promote the ferroptosis of ovarian cancer cells induced by erastin and RSL3, which is related to directly targeting ACSL4 and increasing its expression." (PMID 36408273, 2022). "We observed in this independent set of samples that FOLR1, ITGB3, ITGA5 and ACSL4 have higher expression for majority of the ovarian cancer cases compared to the non-ovarian cases." (PMID 37884576, 2023).
pancreatic cancer (17 papers, 2016 to 2025). "The results revealed that NCOA6 expression was positively related to SCD1 expression in pancreatic cancer tissues and negatively related to ACSL4 expression." (PMID 40065720, 2025). "To verify the expressions of NCOA6, SCD1 and ACSL4 in patient tissues, we randomly selected 30 patients with pancreatic cancer from our center, and immunohistochemical staining was performed on their paraffin-embedded tissues with corresponding antibodies." (PMID 40065720, 2025). "We found that NCOA6 can affect the expressions of SCD1 and ACSL4 in pancreatic cancer cells.NCOA6 knockdown upregulated the expression of ACSL4 and downregulated the expression of SCD1." (PMID 40065720, 2025). "In pancreatic tumor, cancer-associated fibroblast (CAF)-derived long-chain fatty acid–CoA ligase 4 (ACSL4)-targeting miRNAs suppress ferroptosis and induce gemcitabine resistance." (PMID 40740652, 2025). "CAFs regulate lipid metabolism in pancreatic cancer cells by secreting exosomes containing miRNAs (miR-3173-5p) that target ACSL4, thereby inhibiting ACSL4 expression and reducing ferroptosis." (PMID 40733146, 2025). "NCOA6 knockdown in pancreatic cancer cells results in the downregulation of ACSL4 and the upregulation of SCD1, thus enhancing the lipid peroxidation caused by RSL3 in pancreatic cancer cells and increasing their sensitivity to ferroptosis." (PMID 40065720, 2025). "ACSL4 was upregulated inNCOA6-knockdown pancreatic cancer cells." (PMID 40065720, 2025). "ACSL4 facilitates cell sensitivity to chemotherapy in pancreatic cancer." (PMID 35242038, 2022). "Similarly to our results, molecular biological studies on ferroptosis in pancreatic cancers revealed that ARF6-silencing increased the expression of ACSL4, which enrich cellular lipid membrane with long PUFAs27, resulting in RLS3-induced ferroptotic cell death of PANC-1 and MIA-Paca249." (PMID 38388563, 2024). "Our study revealed that the NCOA6 gene regulates the sensitivity of pancreatic cancer cells to oxidative stress by influencing SCD1 and ACSL4." (PMID 40065720, 2025). "A related study found that knockdown of ARF6 in pancreatic cancer cell lines strongly enhanced the sensitivity of pancreatic cancer PANC-1 cell lines to RSL3-induced ferroptosis and was accompanied by an increase in the protein expression level of ACSL4." (PMID 37580745, 2023). "Mechanistically,NCOA6 knockdown promotes the expression of ACSL4 while inhibiting the expression of SCD1, resulting in changes in lipid metabolism, sensitivity to RSL3-induced ferroptosis, and sensitivity to gemcitabine in pancreatic cancer." (PMID 40065720, 2025). "Alternatively, the suppression of the lipid flippase solute carrier family 47 member 1 (SLC47A1) enhances ferroptosis by favoring the ACSL4–sterol O-acyltransferase 1 (SOAT1) pathway over the ACSL4–LPCAT3 pathway, leading to the production of PUFA cholesterol esters in pancreatic cancer cells." (PMID 39090114, 2024). "Meanwhile, a negative correlation between ARF6 and ACSL4 expression was also confirmed in tissue specimens from pancreatic cancer patients." (PMID 37580745, 2023). "Knockdown ofNCOA6 promotes the expression of acyl coenzyme a synthase long chain family member 4 (ACSL4) while inhibiting the expression of stearoyl coenzyme a desaturase 1 (SCD1), resulting in changes in lipid metabolism and sensitivity to RSL3-induced ferroptosis in pancreatic cancer cells." (PMID 40065720, 2025).
diabetes (16 papers, 2014 to 2026). "Some studies have shown that an increase in ACSL4-induced ferroptosis is linked to the progression of diabetes, diabetic nephropathy, and diabetes myocardial injury." (PMID 39741964, 2024). "This study investigated the roles of ACSL4-mediated ferroptosis and autophagy in the mechanisms underlying diabetic liver injury, emphasizing their interconnection." (PMID 39741964, 2024). "Studies have indicated that ferroptosis induction by ACSL4 plays a vital role in aggravating the effects of diabetes and its associated complications, such as diabetic cardiomyopathy, diabetic nephropathy, and diabetic retinopathy." (PMID 39741964, 2024). "In addition, the abnormal expression of ACSL4 is closely associated with diabetes, atherosclerosis, obesity, and a series of malignant tumors." (PMID 32859232, 2020). "In addition to ACSL1, ACSL4 has been implicated in diabetes and complications." (PMID 41288931, 2025). "Immunohistochemical results suggested that ACSL4 was mainly highly expressed in epidermal keratinocytes of patients and rats with diabetes mellitus." (PMID 40785592, 2025). "In accordance with the results of NKAα1 overexpression, administration of Hamaudol prevented diabetes‐induced protein upregulations of ACSL4 and Cathepsin B, and induced autophagy in diabetic mouse aortae." (PMID 39902679, 2025). "The results of the Western blotting and IHC analyses also showed that the level of the ACSL4 protein was significantly higher in the diabetic liver injury group." (PMID 39741964, 2024). "Our results also indicated that ACSL4 levels increased in diabetes and were degraded through the autophagy-lysosomal pathway." (PMID 39741964, 2024). "According to WB results, diabetes increased the expression of cyclooxygenase 1 (Cox1) and fatty acid coenzyme A ligase (Acsl4) proteins in the ferroptosis pathway in myocardial tissue." (PMID 35909950, 2022). "Endothelial dysfunction a common complication in diabetes, is influenced by ACSL4." (PMID 41288931, 2025). "The ability of ACSL4 to induce ferroptosis in diabetes-related complications has been reported." (PMID 40785592, 2025). "Previous studies have suggested the involvement of ferroptosis in diabetes-induced liver pathology, but whether ACSL4-mediated ferroptosis leads to diabetic liver injury is worth our further study." (PMID 39741964, 2024). "Furthermore, ferroptosis, partially in part by ACSL4, may serve as a potential therapeutic target for type 2 diabetes mellitus (T2DM)." (PMID 41288931, 2025). "Considering that STZ-induced diabetic mouse is a well-recognized animal model of diabetic retinopathy, we next investigated the effects of ZFAS1/miR-7-5p/ACSL4 axis on endothelial ferroptosis using the STZ mouse model." (PMID 36092160, 2022). "It is worthy to mention here that HFD-mediated reduction in hepatic ACSL4 protein levels in C57/BL6 mice occurs under conditions of excessive obesity, mild to moderate hyperglycemia, hyperinsulinemia, diabetes, and hepatic steatosis." (PMID 24879802, 2014). "Additionally, siRNA-mediated knockdown of ACSL4 improved cell viability and mitigated LPO, confirming that ferroptosis is a key mode of cell death induced by high lipids in diabetes." (PMID 39741964, 2024).
melanoma (16 papers, 2019 to 2026). A malignant, usually aggressive tumor composed of atypical, neoplastic melanocytes. "We conducted a retrospective analysis of 63 patients with melanoma to evaluate associations between ACSL4 expression and overall survival (OS), metastasis-free survival (MFS), and disease-free survival (DFS)." (PMID 41918944, 2026). "Together, these findings position ACSL4 as a promising prognostic biomarker in melanoma and suggest a potential connection between ferroptosis biology and antitumor immunity." (PMID 41918944, 2026). "Following treatments with platinum-based drugs, melanoma cells exhibited higher formation of lipid rafts in the membrane mediated by the ACSL4-LPO axis." (PMID 41188993, 2025). "A375 melanoma cells were subsequently pretreated with iEV-NC, iEV-150, or iEV-150 combined with sh-ACSL4 or sh-CHAC1 for 48 h before being cocultured with CD8+ T cells." (PMID 40860143, 2025). "In this study, we discovered that lipid peroxidation (LPO) promotes the formation of lipid rafts in the membrane, which mediated by Acyl-CoA Synthetase Long Chain Family Member 4 (ACSL4) impairs the sensitivity of melanoma cells to platinum-based drugs." (PMID 39343834, 2024). "Our results provides new insights of ACSL4 into the mechanism of melanoma prognosis and provide a theoretical basis for developing new therapeutic strategies and drugs in the future." (PMID 36313708, 2022). "This is also consistent with the poor prognosis of the low expression of ACSL4 in melanoma in this study." (PMID 35126480, 2022). "Previous studies showed ACSL4 displayed both tumor-promoting and tumor-suppressive functions in different tumor types, while the role of ACSL4 in melanoma was still elusive." (PMID 36313708, 2022). "In this study, mixed-cancer panel found that ACSL4 had different degrees of genetic changes in 21 cancers, among which ACSL4 was most prone to genetic changes in Endometrial carcinoma, Melanoma and Sarcoma." (PMID 35126480, 2022). "The metastases included in this tissue array were gastrointestinal in origin so the performance of ACSL3 and ACSL4 combined biomarker will need to be assessed in relation to other common metastatic tumours such as those arising from lung, breast and melanoma." (PMID 32286604, 2020). "Acyl coenzyme A (Acyl-CoA) synthetase long-chain family member 4 (ACSL4) promotes ferroptosis by enriching cellular membranes with polyunsaturated fatty acids, yet its prognostic relevance in melanoma remains unclear." (PMID 41918944, 2026). "Both ACSL4 and CHAC1 were positively correlated with miR-150-3p expression, and their low expression levels were associated with poor survival outcomes in melanoma patients in an independent cohort." (PMID 40860143, 2025). "Moreover, knockdown of ACSL4, which prevents the formation of lipid rafts under RL treatment, abrogated the acquired resistance of melanoma cells to cisplatin." (PMID 39343834, 2024). "In contrast, miR-150-3p expression was positively correlated with YAP, ACSL4, CHAC1, and CD8+ T-cell infiltration and iron accumulation in melanoma tissues." (PMID 40860143, 2025). "For example, inhibition of GPX4 or acyl-CoA synthetase long-chain family member 4 (ACSL4), a key enzyme that promotes lipid peroxidation, significantly enhances the efficacy of ICIs in melanoma models." (PMID 40376583, 2025). "In melanoma and fibrosarcoma, overexpression of EGFR and ERBB2 sensitizes tumors to ferroptosis-inducing treatments through activation of the RAS/RAF/c-Myc/ACSL4 signaling axis." (PMID 40846695, 2025). "We observed expressions of ferroptosis related proteins including ALOX5, PEBP1, ACSL4 and ZEB1 in melanoma, which showed a strong cytoplasmic staining." (PMID 36313708, 2022). "In the 9 gene signatures, by qRT-PCR, we found that significant differences in the expression of ABCC1, ACSL4 and ALOX5 between normal skin cell lines and melanoma cell lines." (PMID 35354376, 2022).
melanoma (continued). "Furthermore, ACSL4 and CHAC1 expression levels were significantly lower in melanoma tissues than in matched normal samples." (PMID 40860143, 2025). "Our results reveal that ACSL4-dependent LPO is a key regulator of lipid rafts formation and antitumor immunity, and that disrupting lipid rafts has the potential to enhance platinum-based drug-induced immunogenic ferroptosis and pyroptosis in melanoma." (PMID 39343834, 2024). "While investigating the association between expression of hub OS genes and SKCM clinical features, we discovered that patients with metastatic melanoma had significantly increased expression of AKAP9, VPS13C, and ACSL4, while HMOX2 demonstrated higher expression in patients with primary melanoma." (PMID 33663112, 2021). "Intriguingly, patients with primary melanoma or higher tumor stage had significantly worse outcomes, which suggested that AKAP9, VPS13C, ACSL4, and HMOX2 might play a vital role in the overall survival of SKCM through mediating cancer growth and metastasis." (PMID 33663112, 2021). "Our findings revealed a negative correlation between the melanoma and tissue-resident memory T cell (TRM) pathway and the gene ACSL4." (PMID 40612574, 2025).
cervical cancer (15 papers, 2022 to 2026). A primary or metastatic malignant neoplasm involving the cervix. "Various ferroptosis-associated traditional signals such as SLC7A11, GPX4, and ACSL4 have been uncovered in cervical cancer, and it seems that circRNAs provide prominence to regulate ferroptosis-related signals in cervical cancer." (PMID 37065473, 2023). "Moreover, the ACSL4 level was positively associated with the circLMO1 level in 30 cervical cancer tissues (r2 = 0.3781, p<0.01)." (PMID 35321435, 2022). "Following the administration of siRNA to reduce ACSL4 expression in cervical cancer cells, the inhibitory effect of oleanolic acid on cell survival and proliferative capability was reversed, and a decrease in ROS levels and GPX4 was found." (PMID 40070365, 2025). "ACSL4 was also significantly up-regulated in cervical cancer (HeLa) cells and xenograft models after oleanolic acid therapy." (PMID 40070365, 2025). "CircLMO1 enhances ferroptosis and the antiproliferation of cervical cancer cells by upregulating ACSL4, which is reversed by miR-4291 overexpression or ACSL4 underexpression." (PMID 38892270, 2024). "As downregulated circRNA in cervical cancer tissues, circLMO1 overexpression decreases the proliferation and invasion and increases the ferroptosis of cervical cancer cells via the miR-4192/ACSL4 axis." (PMID 38778030, 2024). "Except sorafenib, natural product oleanolic acid inhibited cervical cancer Hela cell proliferation through modulation of the ACSL4 ferroptosis signaling pathway." (PMID 37065442, 2023). "Studies also found that oleanolic acid inhibits cervical cancer HeLa cell proliferation through modulation of the ACSL4 ferroptosis signaling pathway." (PMID 37350944, 2023). "CircLMO1 overexpression repressed cervical cancer growth and metastasis through sponging miR-4291, de-repressing ACSL4 expression, and thus accelerating ferroptosis." (PMID 35321435, 2022). "Using siRNA to inhibit the expression of ACSL4 in cervical cancer cells, the suppression effect of OA on cell proliferation and viability was cancelled." (PMID 35910359, 2022). "CircLMO1 triggers ferroptosis through sponging miR-4291, thereby enhancing ACSL4 expression in cervical cancer cells." (PMID 35321435, 2022). "In cervical cancer cells, oleanolic acid can induce ferroptosis by promoting ACSL4, while interfering with ACSL4 expression can reduce the inhibitory effect of oleanolic acid on tumor cell viability and proliferation." (PMID 35775079, 2022). "Conclusion: circLMO1 is downregulated in cervical cancer and circLMO1 overexpression inhibits cervical cancer growth and metastasis by promoting miR-4291/ACSL4-mediated ferroptosis." (PMID 35321435, 2022). "Overexpression of miR-4291 or knockdown of ACSL4 reversed the effect of circLMO1 on facilitating ferroptosis and repressing cervical cancer cell proliferation and invasion." (PMID 35321435, 2022). "Research has shown that OA activates ferroptosis in cervical cancer cells by enhancing ACSL4 expression and then a significant decrease in the viability and proliferative capacity of cancer cells was observed after exposure to OA." (PMID 36497375, 2022). "Taken together, these data demonstrate that circLMO1 inhibits cervical cancer cell proliferation and invasion by facilitating miR-4291/ACSL4-mediated ferroptosis." (PMID 35321435, 2022). "CircLMO1 suppresses cervical cancer growth and promotes cervical cancer cell ferroptosis through up-regulating ACSL4 expression." (PMID 36266731, 2022). "ACSL4 silencing reverses the effects of TRIM37 knockdown in cervical cancer cells." (PMID 40158112, 2025). "After knockdown of ACSL4 expression in cervical cancer cells, the anticancer effect of oleanolic acid was counteracted, resulting in a decrease in reactive oxygen species and GPX4 levels, suggesting that OA activates ferroptosis in cervical cancer cells by promoting ACSL4 expression." (PMID 38292937, 2024).
cervical cancer (continued). "In addition, circLMO1 inhibits the growth of cervical cancer cells by adsorbing miR-4192 to repress the target gene ACSL4, which promotes ferroptosis in cervical cancer cells." (PMID 37152286, 2023). "Finally, we assessed the role of circLMO1/miR-4291/ACSL4 axis in regulating cervical cancer cell ferroptosis, proliferation, and invasion." (PMID 35321435, 2022). "CircLMO1 acted as a tumor suppressor of cervical cancer by regulating miR-4291/ACSL4-mediated ferroptosis, and could be a promising biomarker for the clinical management of cervical cancer." (PMID 35321435, 2022). "Currently, ACSL4 is studied in cervical cancer mostly in relation to drug therapy." (PMID 36497375, 2022). "Interestingly, ACSL4 was highly expressed in cervical cancer cells treated with OA." (PMID 35910359, 2022). "In cervical cancer cells, DHA treatment aggravated the levels of oxidative stress, which was manifested by the accumulation of ROS, LPO and MDA, and the upregulation of ACSL4." (PMID 37065442, 2023).